INS (insulin)
Diseases named in the same sentence as INS in open-access papers (continued):
Sharing a sentence is not in itself a finding about the gene and the disease.
acne (continued). "Tan and Bhate suggested that the sugars in dairy products and chocolate trigger insulin secretion, activating signalling pathways that lead to increased keratinocyte proliferation, and consequently to the formation of acne lesions." (PMID 34133464, 2021). "Individuals that suffer from acne usually have high levels of androgens, progesterone, insulin, and IGFs, and, on the contrary, low levels of estrogen." (PMID 34834345, 2021). "Those who consume low-insulinotropic paleolithic diets exhibit much lower insulin/IGF-1 signaling, which is linked to a reduced occurrence of acne." (PMID 34203830, 2021). "T, SHBG, and FAI were negatively correlated (−0.13, −0.10, and −0.11, respectively) (P < 0.05), while acne, hirsutism, fasting insulin, and HOMA-IR were positively correlated (0.079, 0.11, 0.084, and 0.082, respectively) (P < 0.05)." (PMID 34744814, 2021). "Insulin sensitivity was also improved in group A suggesting the possible use of metformin and diet as a potential adjuvant therapy for male patients with acne." (PMID 33255783, 2020). "Another study of 243 acne patients and 156 controls also found that fasting insulin levels were significantly higher in acne patients." (PMID 31824416, 2019). "Isotretinoin treatment significantly decreased Ferriman-Gallwey score, free testosterone, insulin level, hemoglobin level, acne score, and ovarian volume." (PMID 31080813, 2019). "Recent data draw attention to the effect of body composition, insulin resistance, and adipocytokines to acne vulgaris (AV) development." (PMID 30761880, 2019). "Taken together, Western diet and puberty, in the conditions of acne and hidradenitis suppurativa, increase insulin signaling and activate mTORC1." (PMID 31824416, 2019). "The number of acne lesions, sex hormone levels, and insulin markers were compared at baseline and after intervention." (PMID 28513546, 2017). "Recent evidence underlines that dietary factors, especially hyperglycaemic carbohydrates and milk consumption, increase insulin/IGF-1 signalling promoting acne." (PMID 28927457, 2017). "The study included male and female patients with mild to severe acne and tracked adiponectin in addition to insulin/insulin resistance markers." (PMID 28513546, 2017). "Increased IGF-1 signalling of puberty superimposed with insulin signalling of Western diet (hyperglycaemic carbohydrates and milk) provide the input signals for disturbed acne metabolomics including mTORC1-S6K1-mediated insulin resistance." (PMID 28927457, 2017). "All 22 subjects with resistant acne had impaired metabolic profiles and decreased insulin sensitivity." (PMID 28513546, 2017). "The most common included late menses (69%, ±4.31, 95% CI); hirsutism (66%, ±4.20, 95% CI); acne (51%,±4.52, 95% CI); insulin imbalances ( 56%, ±4.63, 95% CI), being overweight (78%, ±4.46, 95% CI) or very overweight, (51%, ±4.61, 95% CI)." (PMID 25481654, 2014). "Typically, these are lowering insulin level, restoration of fertility and regular menstruation, and treatment of hirsutism and acne." (PMID 22194988, 2011). "Insulin also stimulates the synthesis of androgens leading to high sebum production, a recognized correlate of acne severity." (PMID 22253996, 2010). "A retrospective study selected data from 305 women with PCOS and demonstrated that 56.4% of them had acne, while elevated insulin resistance markers and dehydroepiandrosterone sulfate (DHEAS) levels were highly correlated with both the presence and severity of this skin condition." (PMID 41473651, 2025). "Common approaches include oral contraceptives for menstrual regulation, insulin sensitizers (e.g. metformin, pioglitazone, glucagon-like peptide-1 agonists) for metabolic homeostasis, and antiandrogens (e.g. spironolactone, statins) for hirsutism and acne." (PMID 41497317, 2025). "Moreover, insulin-induced lipogenesis produces in SZ95 sebocytes alterations that mimic acne sebum in terms of lipid composition and inflammatory mediators." (PMID 40422250, 2025).
acne (continued). "High insulin levels increase androgen production hence hair growth and acne." (PMID 38196458, 2024). "Both insulin and androgens play a role in the pathogenesis of acne vulgaris." (PMID 39087744, 2024). "Moreover, insulinogenic amino acids contained in milk, which are responsible for the high insulin index of milk, also exacerbate acne lesions." (PMID 38998499, 2024). "According to research, a diet centered around plant-based foods and supplemented with vegan polyphenols may help diminish acne blemishes through microbiota adjustment, inflammation reduction, insulin resistance, and hormonal balance." (PMID 38313941, 2024). "Recent evidence suggests that elevated insulin levels may contribute significantly to acne development through effects on sex hormones, subsequently influencing sebum production and inflammation." (PMID 38556870, 2024). "Higher insulin results in the higher production of hepatic insulin-like growth factors (IGF-1), which is linked with the increased production of sebum from the sebaceous glands, a major factor involved in the pathogenesis of acne." (PMID 39624570, 2024). "Finally, the implication of insulin-mediated responses of the SG will be considered in the context of investigations and therapeutics of acne." (PMID 37727660, 2023). "A better understanding of the mechanisms of insulin action on the SG may stimulate the development of novel therapeutic strategies targeting specific molecular pathways in the management of acne." (PMID 37727660, 2023). "Furthermore, insulin promotes androgen synthesis, resulting in excessive sebum production, a known correlate of acne severity." (PMID 36852374, 2023). "Insulin induces an increase in the size and number of sebocytes, as well as lipogenesis and inflammatory response, contributing to the initiation and aggravation of acne manifestations." (PMID 37727660, 2023). "Acne vulgaris may be induced in the course of disorders that are characterized by abnormal levels, not only of androgens, estrogens, and progesterone but also of insulin and insulin-like growth factor-1." (PMID 37626790, 2023). "Fluctuations in insulin and IGF-1 levels can affect seborrhea, one primary cause of acne." (PMID 37892480, 2023). "What is already clear is that insulin serum levels have been observed to be elevated in patients with acne vulgaris, and that both acne and IR share the hormonal and signal transduction pathways, including insulin-like growth factor-1 (IGF-1) and the mammalian target of rapamycin kinase 1 (mTORC1)." (PMID 37626790, 2023). "Interestingly, the correlations with HOMA, fasting insulin and triglyceride values give indications of the relationship between the metabolic profile and acne occurrence." (PMID 37410088, 2023). "Studies have also shown that an increased insulin level can aggravate acne." (PMID 35677010, 2022). "Moreover, acne that presents with other signs of hormonal imbalance, such as hirsutism, irregular menstruation, altered libido and insulin resistance, should raise clinical suspicion of an acne-associated syndrome." (PMID 34829964, 2021). "A clinical trial investigating oral supplementation of L. rhamnosus SP1 (LSP1) had been reported to bring health benefits to the patients such as LSP1 normalized skin expression of genes involved in insulin signalling and an improvement in the appearance of adult acne." (PMID 34680552, 2021). "In addition, it is well-documented that decreased insulin concentration during intensive exercises can improve hirsutism, acne, and menstrual regularity." (PMID 32429890, 2020). "Insulin signaling is a determining factor in post-adolescence acne vulgaris onset." (PMID 30959761, 2019). "Isotretinoin treatment may have beneficial effects on free testosterone, insulin, acne score, and Ferriman-Gallwey score." (PMID 31080813, 2019). "The mechanism linking high insulin levels and acne may be through the altered proliferation of keratinocytes in the pilosebaceous unit." (PMID 28513546, 2017).
acne (continued). "Though the mechanism by which this diet improves acne is unknown, complex carbohydrates, like resistant starch, insoluble fiber, and fructooligosaccharides, have been correlated with greater insulin sensitivity and less inflammation." (PMID 28513546, 2017). "Furthermore, insulin also stimulates the synthesis of androgens, leading to high sebum production, a recognized correlate of acne severity." (PMID 25977937, 2015). "Endocrine factors involved in acne may be affected by milk consumption because milk is an insulinotropic nutrient and has a high insulinemic index which would increase serum insulin and IGF-1 levels." (PMID 22898209, 2012). "We hypothesized that a low-glycemic index diet would improve facial acne severity and insulin sensitivity." (PMID 22253996, 2010). "High insulin concentrations in the fasting and/or postprandial state may exacerbate acne by increasing the proliferation of basal keratinocytes." (PMID 22253996, 2010). "Overall, microneedling remains an effective therapy for acne, and adjunctive topical insulin may reduce the risk of poor clinical response without increasing adverse events." (PMID 41732375, 2026). "Moreover, certain biogenic amines may influence sebaceous gland activity and hormonal balance, establishing a potential mechanistic link between insulin resistance, androgen excess, and acne vulgaris." (PMID 40806666, 2025). "Obese patients frequently have higher levels of androgen, insulin, and insulin growth factor, which can stimulate sebaceous cell proliferation and differentiation by expressing adipogenicity genes, resulting in increased sebum output and a change in the severity of acne." (PMID 38255795, 2024). "Based on the results of research, IGF-1 related to insulin and a specific inhibitor of Smad3, and IL-17 antibodies related to inflammatory pathways, are expected to become targets for the prevention and treatment of acne-induced PSs, providing potential directions for new drug development." (PMID 38585341, 2024). "Milk and dairy products can increase insulin and IGF-1 levels and activate the nutrient-sensitive kinase mammalian target of rapamycin complex-1 (mTORC1), which promotes anabolic pathways associated with increased seborrhea and follicular hyperkeratosis, both involved in acne development." (PMID 37892480, 2023). "People with decreased insulin sensitivity could be more prone to developing acne lesions." (PMID 37626790, 2023). "It is an insulin-sensitizing medication that may play a role in the interplay between acne and IR." (PMID 36678524, 2022). "Insulin has been reported to decrease in cold conditions, which may imply the possible role of cryotherapy in inhibiting the activation of the signal pathways during acne development." (PMID 36614827, 2022). "It is important to note that many of these plant-based foods and spices may affect more than one factor in acne pathogenesis (e.g., insulin resistance, microbiome modulation, sex hormone balance), so without targeted evaluations, it is difficult to say which mechanism was most clinically relevant." (PMID 28513546, 2017). "Since weight loss as well as higher protein and fiber intake have all been linked to improved insulin sensitivity, it is not clear whether dietary GI played an important role in the improvement of acne." (PMID 22253996, 2010). "Acne vulgaris may be improved by dietary factors that increase insulin sensitivity." (PMID 22253996, 2010). "In the present study, we hypothesized that in the context of weight maintenance and identical macronutrient and fiber intake, the replacement of high GI carbohydrates with low GI carbohydrates would improve acne severity by lowering postprandial insulin concentrations and/or decreasing IR." (PMID 22253996, 2010). "Whey protein increases insulin and IGF-1 signaling, which upregulate androgenic pathways, sebaceous gland activity, and keratinocyte proliferation-major contributors to acne pathogenesis." (PMID 40688823, 2025).
acne (continued). "Endocrinological therapies, including the use of anti-androgens, OCPs, and insulin-sensitizing agents like metformin and acarbose, offer long-term benefits in managing PCOS-related acne." (PMID 40337376, 2025). "Rapid glucose absorption raises insulin and IGF-1 levels, which positively correlate with the severity of acne, stimulating sebum production and androgen synthesis." (PMID 38562266, 2024). "Several studies have revealed noticeably higher insulin serum levels and HOMA values among acne patients compared to the healthy controls; therefore, they indicate the importance of considering IR as a causative factor in acne formation." (PMID 37626790, 2023). "Insulin/IGF-1 and androgens trigger the mTOR pathway, which represents a central node between puberty, diet, and acne onset." (PMID 37727660, 2023). "Serological evidence supports the significance of the mammalian target of rapamycin complex 1 (mTORC1) signaling pathway in the interaction between insulin, androgens, insulin-like growth factor (IGF1), and a high-glycemic-index diet in acne." (PMID 37687224, 2023). "Elevated levels of androgens, insulin, and insulin-growth factor-1(IGF-1) lead to the promotion of hyperkeratosis and hyperseborrhea, resulting in acne formation." (PMID 37626790, 2023). "The results obtained in this article regarding metabolic factors showed statistical significance in terms of insulin concentrations and HOMA index, which were higher in the study group with acne compared to the control group." (PMID 36986218, 2023). "Insulin and IGF-1 are known to increase acne formation by increasing sebum production and conversion of testosterone to dihydrotestosterone." (PMID 36161627, 2022). "With that being said, PI3K⁄Akt activity is not only increased by FGFs but also by other growth factors such as insulin and IGF-1, thus offering a plausible explanation why individuals with metabolic syndrome suffer a more severe onset of acne." (PMID 34829964, 2021). "Acne, T, SHBG, FAI, hirsutism, fasting insulin, and HOMA-IR were significantly correlated with SAS-SS." (PMID 34744814, 2021). "The major hormones like androgens, insulin, and insulin-like growth factor-1(IGF-1) are responsible for the occurrence and development of acne vulgaris." (PMID 34067630, 2021). "In addition, a high content of hormones active in the milk could act either on insulin levels leading to infundibular hyperkeratinization or that on pilosebaceous follicles (5-α-androstenedione and 5-α-pregnanedione), thus leading to worsening of acne." (PMID 33902622, 2021). "Previously, clinical investigations have linked low insulin sensitivity and high glycemic load diet, which can augment insulin/insulin-like growth factor-1 (IGF-1) signaling, with the pathogenesis of acne." (PMID 34466486, 2019). "Insulin, insulin-like growth factor-1 (IGF-1), and defective nuclear transcription factor forkhead box protein O1 (FOXO1) promote acne by stimulating sebaceous lipogenesis and androgen signaling." (PMID 30959761, 2019). "Increased insulin-IGF-1 signaling in acne vulgaris activates PI3K-Akt-mTORC1 signaling cascade and plays a key role in the Western-diet induced acne." (PMID 28036057, 2016). "Moreover, another group has proposed a hypothesis for the diet-induced impact of insulin/IGF-1 signaling in acne, as both high glycemic load and dairy proteins increase the serum levels of insulin and IGF-1, important promoters of sebaceous glands and sebaceous lipogenesis." (PMID 22898209, 2012). "Several different hormones and growth factors, including androgens, estrogens, glucocorticoids, insulin, IGF- 1, fibroblast growth factors, and epidermal growth factors, are involved in the pathogenesis and the progression of acne, through their binding with high-affinity receptors." (PMID 40358870, 2025).
acne (continued). "The importance of the insulin/IGF-1 pathway in acne pathogenesis is also strengthened by the higher prevalence of acne in Western countries, therefore highlighting the role of the high-glycaemic load diet in acne onset and exacerbation." (PMID 40422250, 2025). "Such diets increase insulin and insulin-like growth factor 1 (IGF-1) levels, which then stimulate sebum production and androgen hormone release, which ultimately results in the development of acne." (PMID 39624570, 2024). "Insulin and insulin-like growth factor (IGF-1) can promote increased sebum production and the growth of keratinocytes, which leads to clogged pores and the formation of acne lesions." (PMID 38998499, 2024). "In these conditions, IR may be a leading factor in the pathogenesis of acne, and in men, Metformin treatment may reduce the Global Acne Grading System (GAGS) score by enhancing insulin sensitivity." (PMID 36678524, 2022). "By contrast, a high-glycemic diet and excessive dairy product intake may activate insulin/IGF-1 signaling, stimulating mTORC1 and enhancing keratinocyte proliferation, and hormone production, leading to acne vulgaris." (PMID 35966699, 2022). "The data are consistent with the observation of elevated FFAs in insulin resistant subjects, and the increases of linoleic acids (polyunsaturated FFA), oleic acids (monounsaturated FFA), and palmitic acids (saturated FFA) in acne subjects." (PMID 31951642, 2020). "Both the presence and the severity of acne positively correlated with glycemic load, but not with insulin or insulin resistance markers." (PMID 28513546, 2017). "Recent studies have shown that elevated levels of serum IGF-I correlate with overproduction of sebum and acne as a result of IGF-I and insulin induced lipogenesis of sebaceous glands, probably by induction of sterol response element-binding protein-1 (SREBP-1)." (PMID 27803511, 2016). "Moreover, milk and dairy products act as enhancers of insulin/IGF-1 signalling, supporting sebaceous lipogenesis and acne aggravation through the derepression of the androgen receptor." (PMID 25977937, 2015). "Combining topical insulin with MFR is safe and could accelerate the early acne scar improvement." (PMID 39970082, 2025). "Insulin and IGF-1 activate the PI3K/Akt cascade, which upregulates the nuclear export of forehead box protein O1 (FoxO1), as a key component in the process of acne formation, antagonizing the expression of SREBP-1c and suppressing the transactivation of AR to inhibit lipogenesis." (PMID 34067630, 2021). "Indeed, acne is absent in populations consuming less insulinotropic palaeolithic diets that exclude grains, milk, and dairy products and exhibit much lower insulin/IGF-1 signalling." (PMID 25977937, 2015). "Change in insulin sensitivity was not different between diets (low glycemic index 0.2 ± 0.1 and high glycemic index 0.1 ± 0.1, p = 0.60) and did not correlate with change in acne severity (Pearson correlation r = −0.196, p = 0.244)." (PMID 22253996, 2010). "They found that while fasting glucose levels were not significantly different between the groups, fasting insulin levels were significantly higher in the diseased group; in addition, the HOMA index was higher in those with acne." (PMID 36986218, 2023).